KIF18A (kinesin family member 18A)
Diseases named in the same sentence as KIF18A in open-access papers (continued):
Sharing a sentence is not in itself a finding about the gene and the disease.
colorectal cancer (9 papers, 2018 to 2025). A primary or metastatic malignant neoplasm that affects the colon or rectum. "Specifically, we proved that small inhibitors of KIF18A were feasible to suppress the malignant phenotypes of CIN+ colorectal cancer cells, which provided therapeutic evidences for using KIF18A as a novel target in the treatment of CIN+ colorectal cancer." (PMID 40175357, 2025). "The possible influence of KIF18A inhibition on cell-cycle progression of CIN+ colorectal cancer cells was further evaluated." (PMID 40175357, 2025). "KIF18A knockdown increased the protein expression of p21, and reduced the protein expression of CDK1 and cyclin B1 in NCI-H747, SW620 and CT26 CIN+ colorectal cancer cells, suggesting that KIF18A inhibition triggered G2/M phase arrest." (PMID 40175357, 2025). "KIF18A is overexpressed in several types of cancer, and the overexpression of KIF18A in colorectal cancer was significantly correlated with peritoneal dissemination." (PMID 38372748, 2024). "There is mounting evidence that KIF18A regulates the development of lung cancer, breast cancer, colorectal cancer, and other cancers." (PMID 38372748, 2024). "The study is designed to investigate the effect and molecular mechanism of KIF18A on the progression of colorectal cancer." (PMID 37708299, 2023). "In colorectal cancer, it was obvious that the expression of KIF18A was promoted in tumour tissues (275 vs. 349, P = 0.017)." (PMID 37708299, 2023). "Our data provided a novel role of KIF18A in antitumor immunity of CIN+ colorectal cancer." (PMID 40175357, 2025). "Recently, KIF18A is found to be a mitotic vulnerability in chromosomally unstable cancers, but whether targeting KIF18A affects antitumor immunity in CIN+ colorectal cancer is unknown." (PMID 40175357, 2025). "Our data elucidated a novel role of KIF18A in antitumor immunity of CIN+ colorectal cancer." (PMID 40175357, 2025). "In colorectal cancer, KIF18A is overexpressed and correlated with tumor stage, lymph node metastasis and peritoneal dissemination, while forced KIF18A expression promotes proliferation, migration and invasion of colorectal cancer cells." (PMID 40175357, 2025). "The study focused on the role of KIF18A in colorectal cancer cell progression, migration and invasion, along with the pathways that KIF18A may affect." (PMID 37708299, 2023). "We found that KIF18A whose expression could be up-regulated with the increase of tumor volume as a tumor-promoting gene in colorectal cancer." (PMID 37708299, 2023). "Our data elucidated a novel role of KIF18A in antitumor immunity and anti-PD-1 immunotherapy in CIN+ colorectal cancer." (PMID 40175357, 2025). "In summary, we found that KIF18A inhibition suppressed growth and metastasis, and induced G2/M cell-cycle arrest of CIN+ colorectal cancer cells." (PMID 40175357, 2025). "KIF18A knockdown increased the percentage of G2/M cells rather than G0/G1 and S phases in NCI-H747, SW620 and CT26 CIN+ colorectal cancer cells." (PMID 40175357, 2025). "The potential influence of KIF18A inhibition was also tested in HCT-116 and MC38 CIN- colorectal cancer cells." (PMID 40175357, 2025). "Taken together, our results indicated that KIF18A inhibition suppressed growth and metastasis of CIN+ colorectal cancer cells." (PMID 40175357, 2025). "In our study, introducing with these two shRNAs successfully depleted KIF18A expression in NCI-H747, SW620 and CT26 CIN+ colorectal cancer cells compared with scramble control (SCR)." (PMID 40175357, 2025). "Above all, these data indicated that targeting KIF18A disrupted cell-cycle progression and induced G2/M arrest in CIN+ colorectal cancer cells." (PMID 40175357, 2025). "Correspondingly, we found that KIF18A inhibition apparently restrained proliferation, metastasis and tumor formation, and induced G2/M cell-cycle arrest of CIN+ colorectal cancer cells." (PMID 40175357, 2025).
colorectal cancer (continued). "We found that KIF18A inhibition by short hairpin RNAs (ShRNAs) or small inhibitor AM-1882 suppressed proliferation, migration, invasion and tumor growth and metastasis of CIN+ colorectal cancer cells in vitro and in vivo." (PMID 40175357, 2025). "Moreover, KIF18A inhibition promoted immune infiltration and activation in CIN+ colorectal cancer cells, thus augmented antitumor immunity." (PMID 40175357, 2025). "Moreover, targeting KIF18A disrupted cell-cycle progression and induced G2/M arrest in CIN+ colorectal cancer cells." (PMID 40175357, 2025). "Moreover, KIF18A knockdown by these two shRNAs evidently suppressed cell growth, migration and invasion of NCI-H747, SW620 and CT26 CIN+ colorectal cancer cells." (PMID 40175357, 2025). "KIF18A is required for proliferation of CIN cells derived from triple negative breast cancer or colorectal cancer tumors but is not required in near-diploid cells." (PMID 33619254, 2021). "However, we have never known the influences of KIF18A on colorectal cancer (CRC)." (PMID 37708299, 2023). "In contrast, silencing KIF18A showed no apparently influence on protein expression of p21, CDK1 and cyclin B1 in HCT-116 and MC38 CIN- colorectal cancer cells." (PMID 40175357, 2025).
liver cancer (8 papers, 2014 to 2025). An epithelial or non-epithelial malignant neoplasm that arises from the liver. "Experimental results showed that the expression level of KIF18A in liver cancer cells was significantly higher than that in normal liver cells, and the high expression of KIF18A was associated with the poor prognosis of patients with liver cancer." (PMID 41082523, 2025). "This study provides a new strategy for the prognostic assessment and targeted therapy of HCC and reveals the important role of KIF18A in the development of liver cancer." (PMID 41082523, 2025). "We performed immunohistochemistry on liver cancer and pancreatic cancer tissues and corresponding normal tissues to examine the expression of KIF18A protein." (PMID 36830695, 2023). "We performed IHC on liver cancer and pancreatic cancer to confirm the expression of KIF18A protein in cancers and normal tissue samples." (PMID 36830695, 2023). "Studies have reported that KIF18A promotes the proliferation, invasion, and migration of liver cancer cells by promoting cell cycle signaling pathways." (PMID 36287187, 2022). "Among them, MCODE 1 mainly comprised the mutations of CDK1, KIF2C, KIF18A, CENPA, and PLK1, which take part in the tumorigenesis and progression of liver cancer." (PMID 34414037, 2021). "KIF18A expression levels were found to be markedly higher in liver cancer tissues compared to adjacent normal liver tissues." (PMID 31392101, 2019). "Our previous experiments demonstrated the expression of KIF18A in human liver cancer tissue and paracancerous tissue at the mRNA level, and we now show KIF18A protein expression in these tissues." (PMID 29466986, 2018). "The positive rate of KIF18A expression was significantly higher in liver cancer tissues than that in adjacent normal liver tissues (ANLT) from HCC patients [65.6% (21 of 32) vs. 25.0% (8 of 32), P=0.001]." (PMID 25431949, 2014). "The overexpression of KIF18A could significantly promote the proliferation, invasion and migration abilities of liver cancer cells, while the knockdown of KIF18A inhibited these cellular behaviors." (PMID 41082523, 2025). "The level of KIF18A protein was higher in liver cancer tissues than adjacent tissues." (PMID 29466986, 2018). "This indicates that abnormal expression of KIF18A in liver cancer may lead to abnormal regulation of mitosis, but the specific molecular mechanism requires further research and confirmation." (PMID 29466986, 2018). "Semi-quantitative RT-PCR results showed that KIF18A was significantly up-regulated in liver cancer tissues compared with ANLT in 16 of 20 (80%) HCC patients, while its expression in 8 cases of normal liver tissues from hepatic hemangioma' surrounding liver tissues was undetectable." (PMID 25431949, 2014). "In addition, KIF18A could promote EMT of liver cancer cells, downregulate E-cadherin and upregulate the expression of N-cadherin." (PMID 41082523, 2025). "Therefore, KIF18A may promote the proliferation, invasion, and EMT of liver cancer cells by activating the 5-LOX-dependent arachidonic acid pathway." (PMID 41082523, 2025). "The overexpression of KIF18A had poor OS, DSS, and PFI in adrenocortical carcinoma (ACC), kidney renal clear cell carcinoma (KIRC), kidney renal papillary cell carcinoma (KIRP), brain lower-grade glioma (LGG), liver cancer (LIHC), lung adenocarcinoma (LUAD), and pancreatic cancer (PAAD)." (PMID 36830695, 2023).
lung adenocarcinoma (8 papers, 2020 to 2025). A carcinoma that arises from the lung and is characterized by the presence of malignant glandular epithelial cells. "In lung adenocarcinoma cells, KIF18A knockdown caused apoptosis and G2/M phase arrest, as well as a reduction in their capability for proliferating both in vitro and in vivo." (PMID 37965453, 2023). "Another study revealed that overexpression of KIF18A was independently associated with poor OS of lung adenocarcinoma patients and demonstrated that KIF18A knockdown significantly inhibited the proliferation of cells both in vitro and in vivo." (PMID 36837615, 2023). "Association between Kif18A protein expression and clinical parameters in patients with lung adenocarcinoma." (PMID 31977917, 2020). "As a member of KIFs, KIF18A can independently predict unfavorable prognosis in lung adenocarcinoma; overexpression of KIF18A can promote cell proliferation and inhibit apoptosis." (PMID 34557409, 2021). "The expression of the Kif18A protein in lung adenocarcinoma tissues was higher than in the corresponding paracancerous normal tissues (P = .035)." (PMID 31977917, 2020). "The expression of the Kif18A protein in lung adenocarcinoma tissues was significantly higher than in the corresponding paracancerous normal tissues (P = .006)." (PMID 31977917, 2020). "The transcriptional and translational levels of KIF18A were both increased in lung adenocarcinoma." (PMID 37965453, 2023). "Silencing KIF18A induced apoptosis in lung adenocarcinoma cells and blocked the cell cycle at G2/M phase, while overexpression of KIF18A might promote cell proliferation and inhibit apoptosis." (PMID 32851080, 2020).
esophageal cancer (6 papers, 2023 to 2025). A primary or metastatic malignant neoplasm involving the esophagus. "KIF18A is upregulated in esophageal cancer patients, while silencing KIF18A decreases proliferation, migration and invasion of esophageal cancer cells." (PMID 40175357, 2025). "In previous studies, it was reported that KIF18A was involved in cell proliferation, migration as well as invasion of esophageal cancer and chromosomally unstable tumor cells." (PMID 37708299, 2023). "KIF18A is overexpressed in esophageal carcinoma, and knockdown of KIF18A can reduce cell proliferation and migration and enhance radiosensitivity." (PMID 36830695, 2023). "Previous studies have reported that knockdown of KIF18A resulted in decreased cell proliferation and increased apoptosis in LUAD cells and inhibited proliferation, migration, and invasion in esophageal cancer cells." (PMID 39822281, 2025).
ovarian carcinoma (6 papers, 2021 to 2025). A malignant neoplasm originating from the surface ovarian epithelium. "Disruptions of KIF18A activity can lead to abnormal chromosome segregation and aneuploidy, which is common in breast and ovarian cancers." (PMID 41369352, 2025). "Given the potential of KIF18A inhibition in ovarian cancer, we conducted preclinical evaluations of a novel KIF18A inhibitor, ATX020 to assess its activity in various HGSOC cell line models including platinum-resistant and PARPi-resistant cell line models." (PMID 41369352, 2025). "Our study found that a subset of breast and ovarian cancer cell lines with CCNE1 amplification were sensitive to KIF18A inhibition but resistant to CDK4–CDK6 inhibition." (PMID 38151625, 2024). "Our KIF18A inhibitors faithfully phenocopy the mitotic and viability effects observed with KIF18A KD in a panel of breast and ovarian cancer cell lines." (PMID 38151625, 2024). "Collectively, these data highlight the identification of breast and ovarian cancer cell lines with a heightened KIF18A dependency; these findings motivated us to perform a small-molecule screen to identify inhibitors of KIF18A motor activity." (PMID 38151625, 2024). "In particular, KIF18A, a member of the kinesin-8 family, has been shown to be overexpressed in malignant tumors like colon, breast, lung, pancreas, prostate, cervix, and ovarian cancers." (PMID 35153752, 2021). "To investigate how KIF18A influences HGSOC cell growth, we focused on three representative ovarian cancer cell lines (A2780, OVCAR3, and OVCAR8), given that they represent a range of ATX020 sensitivity and varying cisplatin and olaparib responses." (PMID 41369352, 2025). "KIF18A inhibitor treatment across the large-scale pan-cancer PRISM panel (629 cell lines) revealed that 25% of cancers overall and 32% of ovarian cancers exhibited strong KIF18A dependency." (PMID 38279026, 2024). "All CIN cell lines evaluated (HeLa and two ovarian cancer cell lines; SKOV3 and OVCAR3) demonstrated a significant mitotic arrest with depletion of KIF18A (p <0.0001 for all cell lines)." (PMID 39677807, 2024). "Thus, our results support the idea that KIF18A inhibition may serve as a promising therapeutic treatment for CIN tumor types including breast, colorectal, cervical, and ovarian cancer." (PMID 38410188, 2024).
lung carcinoma (4 papers, 2020 to 2022). "The aim of this study was to investigate the expression of Kif18A in cancerous and paracancerous tissues from 100 patients with nonsmall cell lung cancer (NSCLC)." (PMID 31977917, 2020).
glioblastoma (3 papers, 2022 to 2025). The most malignant astrocytic tumor (WHO grade IV). "By immunohistochemical analysis, we found that high expression of KIF18A was associated with tumor recurrence in glioblastoma patients." (PMID 35464837, 2022). "We also performed immunohistochemical analysis of the KIF18A levels in 94 patients with glioblastoma and the associated surrounding tissues." (PMID 35464837, 2022). "We further demonstrated that GBM tissues expressed KIF18A much higher, and its presentation was associated with recurrence in glioblastoma patients." (PMID 35464837, 2022). "In glioblastoma, KIF18A inhibition suppresses cell growth, migration and invasion, and induces G2/M cell-cycle arrest of glioblastoma cells via interacting with PPP1CA." (PMID 40175357, 2025). "We further investigated the clinical properties and biological functions of KIF18A in glioblastoma carcinogenesis." (PMID 35464837, 2022). "Based on the high levels of KIF18A in glioblastoma patients, we further investigated KIF18A in glioblasts using a shRNA-mediated assay." (PMID 35464837, 2022). "On the other hand, KIF18A could promote the malignant development of glioblastoma by binding to PPP1CA." (PMID 38057879, 2023). "Therefore, KIF18A could be a valuable target for the treatment of glioblastoma." (PMID 35464837, 2022). "In our study, KIF18A was identified as an important gene affecting the occurrence and development of GBM, suggesting that it plays an important role in glioblastoma patients, and its overexpression is related to the proliferation of cancer cells in vivo and in vitro." (PMID 35464837, 2022).
lymph node metastasis (3 papers, 2020 to 2024). "They demonstrated a significant association between KIF18A expression and lymph node metastasis, tumor size, lymphatic invasion, and tumor recurrence." (PMID 38195458, 2024). "Similar results were reported by previous studies that showed KIF18A as an independent predictive factor for the lymph node metastasis and disease-free survival." (PMID 38195458, 2024). "The expression of the Kif18A protein was higher in highly differentiated tumors, in patients with lymph node metastasis (vs no lymph node metastasis), adenocarcinoma, and in stage III NSCLC." (PMID 31977917, 2020). "The expression of the Kif18A protein was higher in patients with lymph node metastasis than in patients without (adenocarcinoma: P = .041; SCC: P = .037)." (PMID 31977917, 2020). "However, the KIF18A expression level in COAD was lower in patients with lymph node metastasis than in patients without lymph node metastasis." (PMID 36830695, 2023).
prostate carcinoma (3 papers, 2022 to 2025). A carcinoma that arises from epithelial cells of the prostate gland. "Functionally, circ_CCNB2 can inhibit autophagy in prostate cancer cells by regulating genes targeted by the miR-30b-5p/KIF18A axis, thereby improving the sensitivity of radio-resistant prostate cancer to radiotherapy." (PMID 41049007, 2025). "It was proved that the knockdown of circ_CCNB2 increased the radiosensitivity of PCa through repressing autophagy by the miR-30b-5p/KIF18A axis, but no biological function of CCNB2 in prostate cancer has been found." (PMID 35360870, 2022).
triple-negative breast carcinoma (3 papers, 2021 to 2025). An invasive breast carcinoma which is negative for expression of estrogen receptor (ER), progesterone receptor (PR), and human epidermal growth factor receptor 2 (HER2). "Supporting KIF18A’s therapeutic promise in genomically unstable cancers like triple-negative breast cancer and high-grade serous ovarian cancers, multiple KIF18A inhibitors have been developed and were recently reviewed by Chen and colleagues." (PMID 40002279, 2025).
adrenocortical carcinoma (2 papers, 2021 to 2023). "In addition, KIF18A was reported to be associated with tumour immune cell infiltration in adrenocortical carcinomas." (PMID 34760691, 2021).
Infertility (2 papers, 2022 to 2024). "We previously showed that infertility was 67% penetrant in Kif18a deficient (Kif18agcd2/gcd2) F2 progeny from an intersubspecific cross between the classic inbred strain C57BL/6J (B6) and the wild-derived inbred strain CAST/EiJ (CAST)." (PMID 39677807, 2024). "This search revealed that in the case of NANOS1 overexpression, three infertility related genes (CREBBP, CCNB1, and NPAS2) and five cancer-germ cell genes (CENPL, ERCC6L, KIF18A, SIAH1, and TRIM71) were present in three clusters." (PMID 35743036, 2022). "We found that CAST mice, which exhibit high penetrance of infertility in the absence of Kif18a, had significantly higher expression of Apc7 in juvenile and adult testicular tissue, as well as reduced expression of Apc5 in fetal ovarian tissue compared to B6 mice." (PMID 39677807, 2024).
influenza (2 papers, 2016 to 2020). An acute viral infection of the respiratory tract, occurring in isolated cases, in epidemics, or in pandemics; it is caused by serologically different strains of viruses (influenzaviruses) designated A, B, and C, has a 3-day incubation period, and usually lasts for 3 to 10 days. "Therefore, a single medication targeting KIF18A could have multiple applications in both cancer and infectious diseases, such as influenza." (PMID 32253833, 2020). "We quantified the expression of four human mRNAs, two mRNAs that are significantly reduced during influenza infection (CHML and KIF18A, cluster 1) and two mRNAs that were less affected by infection (MYC and CDKN1B, cluster 3)." (PMID 27525483, 2016).